C9orf72 (C9orf72-SMCR8 complex subunit)
Diseases named in the same sentence as C9orf72 in open-access papers (continued):
Sharing a sentence is not in itself a finding about the gene and the disease.
liposarcoma (3 papers, 2012 to 2020). A usually painless malignant tumor that arises from adipose tissue. "At present, the four major ALS-associated genes are the chromosome 9 open reading frame 72 (C9ORF72), Cu-Zn superoxide dismutase 1 (SOD1), TAR DNA-binding protein 43 (TARDBP), and fusion in malignant liposarcoma/translocation in liposarcoma (FUS/TLS), in addition to at least other 40 genes." (PMID 32487123, 2020).
lysosomal storage disorder (3 papers, 2022 to 2024). "Lysosomes hold potential as an attractive target for therapeutic intervention in ALS, as in addition to VCP, several other ALS associated genes have a role in lysosomal homeostasis (C9orf72, TARDBP, TMEM106B, TBK1, OPTN, SQSTM1) and several lysosomal storage diseases manifest neurological features." (PMID 39593143, 2024).
multiple sclerosis (3 papers, 2018 to 2023). A progressive autoimmune disorder affecting the central nervous system resulting in demyelination. "A possible correlation of C9orf72 repeat expansion with multiple sclerosis (MS) has been investigated previously." (PMID 37511014, 2023). "Interestingly, Case 4 with AD had a cousin with a diagnosis of multiple sclerosis (MS); no DNA from the cousin was available for genotyping of a possible C9orf72 expansion." (PMID 30550541, 2018).
retinal degeneration (3 papers, 2019 to 2024). Degeneration of the retina. "It will be highly prudent to determine how common retinal degeneration is within other C9ORF72-deficient vertebrate models, such as the mouse or rat to determine whether retinal pathology is a universal feature of C9ORF72 loss of function." (PMID 38658168, 2024). "Similarly, we observed a considerable exacerbation of retina degeneration in flies expressing C9orf72 DPRs associated with ArfGAP-1 or ERGIC-53 downregulation." (PMID 37566088, 2023). "Atx2 also regulates retinal degeneration due to FUS as well as the poly-glycine-arginine repeats derived from the ALS genes C9ORF72." (PMID 31593562, 2019). "Overexpression of human Atx2 with intermediate length polyQ expansion enhances C9ORf72 induced neuronal toxicity in mammalian neuronal culture and enhances TDP43 induced retinal degeneration." (PMID 31593562, 2019).
spinocerebellar ataxia type 2 (3 papers, 2021 to 2024). A subtype of type I autosomal dominant cerebellar ataxia (ADCA type I) characterized by truncal ataxia, dysarthria, slowed saccades and less commonly ophthalmoparesis and chorea. "Beyond C9ORF72, studies have identified CAG repeat expansion in the ataxin-2 gene (ATXN2) as a genetic cause of spinocerebellar ataxia type 2 (SCA2) and ALS." (PMID 33732107, 2021). "Interestingly, ATXN2 with intermediate PolyQ repeats is associated not only with spinocerebellar ataxia type 2 (SCA2), but also with ALS, serving as a risk factor for C9ORF72-linked ALS." (PMID 37006471, 2023).
systemic lupus erythematosus (3 papers, 2016 to 2021). An autoimmune multi-organ disease typically associated with vasculopathy and autoantibody production. "Gain‐of‐function mechanisms are likely the main drivers of C9orf72 disease because C9orf72 knockout mice develop mainly alterations of the peripheral immune system, reminiscent of systemic lupus erythematosus." (PMID 31858749, 2020). "C9orf72−/− animals display a subset of lupus-like symptoms, namely lymphoid activation and hyperplasia, a characteristic autoantibody profile and evidence of GN." (PMID 26979938, 2016). "Collectively, our data suggest that C9orf72 regulates immune homeostasis and an autoimmune response reminiscent of systemic lupus erythematosus (SLE) occurs in its absence." (PMID 26979938, 2016).
Tremor (3 papers, 2017 to 2023). An unintentional, oscillating to-and-fro muscle movement about a joint axis. "Weakness (18.9%, 0.26 (0.71)) and functional difficulties using hands (16.2%, 0.26 (0.72)) were significantly impaired when CDR® plus NACC FTLD was 0.5 while tremor was the least frequent and severe symptom in C9orf72 mutation carriers." (PMID 36385202, 2023).
type 2 diabetes (3 papers, 2019 to 2023). "However, another study in mice with the c9orf72 mutation indicated the type II diabetes medication metformin might have therapeutic potential for ALS, indicating ALS risk may be moderated differentially across classes of diabetes medication." (PMID 36747854, 2023). "Metformin, an FDA-approved drug for the treatment of type 2 diabetes, is being repurposed as a small molecule approach to reduce production of toxic C9orf72 non-canonical translation products." (PMID 37138766, 2023).
anemia (2 papers, 2016 to 2018). A reduction in the number of red blood cells, the amount of hemoglobin, and/or the volume of packed red blood cells. "In total, these observations are consistent with Smcr8−/− animals developing a microcytic anemia similar to that found in C9orf72 mutant animals." (PMID 29950492, 2018). "Therefore, loss of Smcr8 led to changes in peripheral blood cell composition that were indistinguishable from those observed in the C9orf72−/− mice, including anemia, thrombocytopenia, and neutrophilia." (PMID 29950492, 2018).
Aphasia (2 papers, 2021 to 2022). An acquired language impairment of some or all of the abilities to produce or comprehend speech and to read or write. "In patients with ALS, TDP-43 lesion allocations are common because it is associated with a pure FTD phenotype or behavior, related to non-fluent aphasia, or linked to the GRN or C9orf72 mutation." (PMID 36226077, 2022).
behavioral variant frontotemporal dementia (2 papers, 2018 to 2023). "Here we assessed [18F]AV‐1451 binding in behavioral variant frontotemporal dementia due to a hexanucleotide repeat expansion in C9orf72, characterized by TDP‐43 pathology." (PMID 30349864, 2018).
Chorea (2 papers, 2021 to 2025). Chorea (Greek for 'dance') refers to widespread arrhythmic involuntary movements of a forcible, jerky and restless fashion. "Repeat expansions in the C9orf72 gene are the second most common genetic cause of chorea in individuals of Caucasian ancestry." (PMID 40584247, 2025).
COVID-19 (2 papers, 2021 to 2023). A disease caused by infection with severe acute respiratory syndrome coronavirus 2. "Further limitations of our study are, first, that the number of carriers of C9orf72 intermediate alleles in the 240 severe COVID-19 patient cohort, as well as in the validation cohort of 201 SARS-CoV-2 infected patients, is small, and one should be cautious with the interpretation of these results." (PMID 34209673, 2021). "Herein, we sought to explore whether intermediate HREs in C9orf72 may be a risk factor for severe COVID-19." (PMID 34209673, 2021). "Hexanucleotide repeat expansions of more than 10 repeats located in the gene C9orf72 were found to be a risk for high pathogenicity of COVID-19 phenotypes, indicating a shared genetic profile between FTD and COVID-19." (PMID 37834358, 2023). "Moreover, further analyses in this work compared severe COVID-19 patients of the first cohort considering MV and NIV requirement as a proxy of high severity of disease to find association with C9orf72 intermediate repeats >10 units." (PMID 34209673, 2021). "Therefore, the cohort of C9orf72 expansion-negative ALS patients from the same geographical area of COVID-19 patients can be considered as representative of the population of that region regarding the genetic background relative to the C9orf72 gene and used to compare COVID-19 patients." (PMID 34209673, 2021). "Genetic analysis for C9orf72 HREs in the 240 COVID-19 patients did not reveal the presence of large (>30 repeats) expansions." (PMID 34209673, 2021).
essential tremor (2 papers, 2013 to 2021). A relatively common disorder characterized by a fairly specific pattern of tremors which are most prominent in the upper extremities and neck, inducing titubations of the head. "Studies have also indicated that intermediate amplification of the C9ORF72 gene (>20 duplicate copies) increases the risk of PD and essential tremor plus PD (ETP), although the specific mechanism requires further exploration." (PMID 33390807, 2021). "Could the C9orf72 repeat expansions account for other neurodegenerative disorders, such as AD, PD, and essential tremor (ET)?" (PMID 24068985, 2013).
hereditary spastic paraplegia (2 papers, 2022 to 2024). Hereditary spastic paraplegias (HSP) comprise a genetically and clinically heterogeneous group of neurodegenerative disorders characterized by progressive spasticity and hyperreflexia of the lower limbs. "First, he offered examples of different diseases (e.g., Huntington's disease, hereditary spastic paraplegia, c9orf72 mutation-associated disorders), discussed variations related to the age of onset, and presented an inspiring case study on hereditary spastic paraplegia in twins." (PMID 36415515, 2022).
latent infection (2 papers, 2020 to 2021). "Then, we could hypothesize that low levels of C9orf72 may be required to maintain some degree of microglial activation to control HSV-2 latent infection." (PMID 33287823, 2020).
Lewy body dementia (2 papers, 2022 to 2023). A progressive form of dementia characterized by the presence of protein deposits called Lewy bodies in the midbrain and cerebral cortex, and loss of cholinergic and dopaminergic neurons. "Of note, amnestic Alzheimer's dementia is a common clinical diagnosis of genetically confirmed FTLD‐TDP in elderly individuals, and in an autopsy series from the State of Florida brain bank, late onset patients with C9orf72 mutations often present with Alzheimer type dementia or Lewy body dementia." (PMID 34823271, 2022).
memory impairment (2 papers, 2018 to 2022). "C9orf72 mutation carriers present more frequently with psychotic symptoms and show more severe memory impairment than sporadic patients." (PMID 29599716, 2018).
Sensory neuropathy (2 papers, 2024 to 2025). Peripheral neuropathy affecting the sensory nerves. "Our results are concordant with current epidemiological studies about the relative frequency of REDs, with the most common being DM1 and C9orf72-ALS/FTD (autosomal dominant) and CANVAS and sensory neuropathy (recessive)." (PMID 39354197, 2024). "Electrophysiological evidence of a sensory neuropathy was observed in 38% of C9orf72 positive patients compared to 21% of C9orf72-negative ALS patients." (PMID 40149536, 2025).
Smith-Magenis syndrome (2 papers, 2017 to 2020). Smith-Magenis syndrome (SMS) is a complex genetic disorder characterized by variable intellectual deficit, sleep disturbance, craniofacial and skeletal anomalies, psychiatric disorders, and speech and motor delay. "The C9orf72 gene product forms a complex with SMCR8 (Smith-Magenis Syndrome Chromosome Region, Candidate 8) and WDR41 (WD Repeat domain 41) proteins." (PMID 32678027, 2020). "A series of studies have shown that the long isoform of human C9orf72 protein forms a complex with SMCR8 (Smith-Magenis Syndrome Chromosome Region, Candidate 8) and WDR41 (WD Repeat domain 41) proteins." (PMID 32678027, 2020).
ataxia telangiectasia (1 paper, 2023). Ataxia-telangiectasia is the association of severe combined immunodeficiency (affecting mainly the humoral immune response) with progressive cerebellar ataxia. "Furthermore, c9orf72 repeat expansion could impair the function of master DNA repair kinases, contributing to ataxia telangiectasia (AT)." (PMID 37566027, 2023).
Caudate atrophy (1 paper, 2017). "In contrast to C9orf72+ cases, caudate atrophy and hippocampal sclerosis were not prominent." (PMID 29216908, 2017).
cerebellar degeneration (1 paper, 2019). Degeneration of the cerebellum. "We tested the relationship between cerebellar degeneration, cognitive syndromes and C9orf72 mutation in ALS patients." (PMID 31133784, 2019). "Cerebellar changes in ALS and FTD have been specifically linked to the C9orf72 repeat expansion, raising the question whether cerebellar degeneration is an important feature of C9+ALS." (PMID 31133784, 2019). "However, there was no specific correlation between cerebellar degeneration and cognitive syndromes or C9orf72 mutations." (PMID 31133784, 2019). "Our data show that cerebellar degeneration is not specific for non-demented patients with ALS and cognitive syndromes or C9orf72 mutations." (PMID 31133784, 2019).
colitis (1 paper, 2025). Inflammation of the colon. "C9orf72 overexpression attenuated DSS‐induced colitis and the intestinal epithelial barrier disorder by promoting the expression of ZO‐1 and Occludin." (PMID 39873292, 2025). "C9orf72 overexpression attenuated DSS‐induced colitis and intestinal epithelial barrier damage by inhibiting the cGAS‐STING pathway." (PMID 39873292, 2025). "C9orf72 overexpression in mice attenuated DSS‐induced colitis and intestinal epithelial barrier damage by stimulating ZO‐1 and Occludin expression." (PMID 39873292, 2025). "The protein levels of ZO‐1 and Occludin were extensively increased in mice with colitis after C9orf72 injection." (PMID 39873292, 2025). "In our study, ZO‐1 and Occludin expression were enhanced in mice with colitis after C9orf72 injection." (PMID 39873292, 2025). "C9orf72 overexpression attenuated dextran sulfate sodium‐induced colitis and the intestinal epithelial barrier damage by inhibiting the cGAS‐STING pathway." (PMID 39873292, 2025). "This study investigated whether C9orf72 could alleviate dextran sulfate sodium (DSS)‐induced colitis in mice and lipopolysaccharide (LPS)‐induced colitis in Caco‐2 cells." (PMID 39873292, 2025). "We found that C9orf72 was observably decreased in dextran sulfate sodium (DSS)‐evoked colitis mice." (PMID 39873292, 2025).
diffuse brain atrophy (1 paper, 2016). "Persons with an expansion mutation of the C9orf72 gene had diffuse brain atrophy compared to healthy controls and sporadic ALS patients." (PMID 27995069, 2016).
Duchenne muscular dystrophy (1 paper, 2013). Duchenne muscular dystrophy (DMD) is a neuromuscular disease characterized by rapidly progressive muscle weakness and wasting due to degeneration of skeletal, smooth and cardiac muscle. "Using knowledge obtained through research into antisense oligonucleotides (ASOs) therapies for diseases such as Duchenne muscular dystrophy (DMD) and myotonic dystrophy type 1, we propose that using such therapy may be a promising approach for treating C9orf72 repeat expansion in c9FTD/ALS." (PMID 24349764, 2013).
familial disease (1 paper, 2025). "In C9orf72 familial disease, astrocytes exhibit TDP-43 pathology and are toxic to motor neurons grown in co-culture." (PMID 41278665, 2025).
glomerular disease (1 paper, 2016). "As prefaced earlier, F4/80+ monocytes were present in high numbers in C9orf72−/− kidneys with evidence of progressive glomerular disease observed by histopathology." (PMID 26979938, 2016).
Immunodeficiency (1 paper, 2018). Failure of the immune system to protect the body adequately from infection, due to the absence or insufficiency of some component process or substance. "While this provides a plausible explanation for the absence of cancer in C9orf72-ALS, it does not explain the apparent absence of immunodeficiency, a hallmark of defective non-homologous end-joining in RIDDLE cells." (PMID 29584802, 2018).
kidney damage (1 paper, 2021). "DPR pathology has not been reported in human in tissues such as the kidney and bladder, even though C9ORF72 is expressed in these organs and C9KO mice show immune-mediated kidney damage." (PMID 33431483, 2021).
laminopathies (1 paper, 2021). "Consistent with previous reports that aged iPSCs display nuclear lamina alterations reminiscent of those observed in laminopathies and cellular senescence, we found that Lamin B1 invaginations increased with iPSC passage number in both control and C9orf72 iPSNs." (PMID 33741069, 2021).
Leukoencephalopathy (1 paper, 2024). This term describes abnormality of the white matter of the cerebrum resulting from damage to the myelin sheaths of nerve cells. "In our analyses, TREM2, TYROBP, and GRN associated with leukoencephalopathy and FTD, show correlated gene expression, however, SMCR8 and WDR41, known to form a complex with C9orf72, did not." (PMID 38469573, 2024).
liver cancer (1 paper, 2023). An epithelial or non-epithelial malignant neoplasm that arises from the liver. "Among them, TOP2A, CENPF, MEFV and C9orf72 directly affect the prognosis of patients with liver cancer." (PMID 38017425, 2023). "PLK3, C9orf72, TRIM22, RNF152, FEZ1 and MEFV were dramatically downregulated in liver cancer patients, but upregulated by CTD treatment in HCC cells." (PMID 38017425, 2023).
Nasu-Hakola disease (1 paper, 2020). "In patients diagnosed with AD we found three C9orf72 expansions, nine DVs in MAPT, five in CSF1R, two in GRN, three in PRNP and one each in SQSTM1, TARDBP and VCP, as well as a homozygous TREM2 DV normally associated with Nasu-Hakola disease." (PMID 30279455, 2020).
polyneuritis (1 paper, 2017). Inflammation of several peripheral nerves. "The genetic C9orf72 status of these patients was (re)analyzed except for the two control patients with vestibular neuritis and polyneuritis, where no DNA was available." (PMID 28408402, 2017).
rapid eye movement sleep behavior disorder (1 paper, 2019). "One study showed a potential involvement of the C9orf72 repeat expansion in rapid eye movement sleep behavior disorder (RBD) by identifying two C9orf72 repeat expansion carriers in a cohort of 344 RBD patients." (PMID 31791419, 2019).
respiratory failure (1 paper, 2023). The significant impairment of gas exchange within the lungs resulting in hypoxia, hypercarbia, or both, to the extent that organ tissue perfusion is severely compromised. "On the other hand, ALS-related morbidities such as respiratory failure could also affect the cognitive status of ALS patients, in addition to their genetic status, such as C9orf72 repeat expansion." (PMID 37333000, 2023).
viral infections (1 paper, 2022). "Interestingly, Herpes Simplex Virus 2 (HSV2) infection in the spinal cord of mice have been shown to decrease C9ORF72 expression, suggesting that this gene may also be modulated by viral infections of the central nervous system." (PMID 35353274, 2022).